GAST (gastrin)
Diseases named in the same sentence as GAST in open-access papers (continued):
Sharing a sentence is not in itself a finding about the gene and the disease.
atrophic gastritis (continued). "Gastrin is often elevated in gastric hypoacidity either due to atrophic gastritis or drug treatment." (PMID 28144230, 2017). "Destruction of parietal cells in atrophic gastritis leads to profound hypochlorhydria which induces G-cell (gastrin-producing) hyperplasia and consequently hypergastrinemia." (PMID 27830096, 2016). "Variations in the pathology of atrophic gastritis have been reported to some degree in genetically engineered mice such as Atp4a−/− and gastrin−/− mice, which are used as models of parietal and glandular cell loss." (PMID 26839577, 2016). "Elevated circulating concentrations of the gastric antral hormone gastrin are found in patients who are hypochlorhydric as a result of atrophic gastritis." (PMID 27323780, 2016). "H. pylori infection results in an elevation of serum gastrin level, in the early stage of infection, and proceeds to the development of atrophic gastritis." (PMID 23280118, 2013). "She remains with mildly elevated serum chromogranin A and gastrin levels (last determination of serum gastrin levels: 591 pg/ml, normal <40), which we attribute to her chronic atrophic gastritis." (PMID 24616764, 2013). "It was reported that 10%-20% of patients with pernicious anemia also have atrophic gastritis of the antrum, with gastrin cell reduction and normal serum gastrin levels." (PMID 24385744, 2012). "It is much more specific than gastrin in cases of type I GCs where hypergastrinemia due to atrophic gastritis occurs (55–85% versus 35–55%)." (PMID 23316222, 2012). "To determine the possible role of RegIα protein, an important downstream regulator of gastrin, in the pathogenesis of atrophic gastritis, we examine the expression of RegIα and its receptor RegIR in rats." (PMID 21949663, 2011). "ELISA assays found that the level of serum gastrin was dramatically increased to 375.0 ± 103.9 ng/mL in atrophic gastritis rats with comparison of 209.6 ± 48.2 ng/mL in normal rats (P < 0.01)." (PMID 21949663, 2011). "In all 3 cases, the serum gastrin level was high and atrophic gastritis was microscopically observed." (PMID 20885936, 2010). "The elevated gastrin concentrations cannot be explained by atrophic gastritis in this study since only one subject had this condition." (PMID 19243587, 2009). "However, gastrin levels can be elevated in patients with atrophic gastritis or in patients receiving proton pump inhibitor therapy." (PMID 37623030, 2023). "A low level of gastrin-17 was reported as a biomarker for atrophic gastritis in the gastric antrum." (PMID 38069253, 2023). "We speculate that a gastric microenvironment composed of H. pylori, atrophic gastritis, and inflammation, which are commonly present in the gastric mucosa adjacent to cancer, may inhibit the local expression of gastrin by cancer cells." (PMID 34976177, 2022). "Fasting 17-gastrin could also be used as an accurate biomarker to assess serologically the onset of gastric atrophy prior to the follow-up endoscopy." (PMID 35603187, 2022). "A recent research supports the use of a panel test that combines pepsinogen, gastrin-17, and anti-Hp antibodies serum assays for screening subjects or populations to identify individuals that are very likely to have atrophic gastritis and should be referred to endoscopy." (PMID 34136433, 2021). "The strength of the present study however is that it removed confounders that may have increased fasting serum gastrin concentrations, such as active H. pylori infection and atrophic gastritis and it also used a well validated radioimmunoassay." (PMID 34867785, 2021). "Increased serum gastrin levels may result from proton pump inhibitors use, atrophic gastritis, and H. pylori infection." (PMID 30611258, 2019). "Gastric atrophy results in lower plasma ghrelin, higher gastrin secretion, a change in gut microbiota, and altered dietary nutrient absorption, which may be associated with the incidence of diabetes." (PMID 28045079, 2017).
atrophic gastritis (continued). "The presence of oxyntic gastric atrophy may indirectly be assessed by low serum pepsinogen I and even better when combined with determination of gastrin." (PMID 28144230, 2017). "This is reflected in the evidence that patients with H. pylori-induced atrophic gastritis and those receiving PPIs exhibited marked differences in 16S rRNA microbiota profiles, co-occurrence networks and predicted pathways, despite similar gastrin levels." (PMID 29095917, 2017). "Prolonged elevated blood levels of gastrin (hypergastrinemia) can occur as a consequence of e.g. atrophic gastritis or pharmacologic inhibition of gastric acid secretion, which interrupts negative feedback mechanisms on gastrin producing G-cells residing in the gastric mucosa." (PMID 23805861, 2013). "The quantitative assay of PCA and gastrin was unable to discriminate AIG from gastric atrophy." (PMID 23251219, 2012). "The role of gastrin on the development of atrophic gastritis (AG) and its relationship with the expression of RegIα in vivo remain unclear." (PMID 21949663, 2011). "To confirm whether the level of gastrin was induced by the proliferative gastric glands, we detected the concentration of gastrin in rats with atrophic gastritis as well as in normal rats." (PMID 21949663, 2011). "The plasma gastrin level might have been slightly elevated in this case as a result of atrophic gastritis." (PMID 20825631, 2010). "The aim of this study was to validate these serum biomarkers, that is pepsinogen A (PGA), pepsinogen C (PGC), PGA/PGC ratio, and gastrin, as screening tests for precancerous lesions: atrophic chronic gastritis (ACG) or Helicobacter pylori-related corpus-predominant or multifocal atrophy." (PMID 12698190, 2003). "In humans, elevated serum gastrin levels are observed in patients with chronic atrophic gastritis due to achlorhydria-induced loss of negative feedback, and hypergastrinemia has been associated with increased risk of gastric neuroendocrine tumors and adenocarcinoma." (PMID 40673273, 2025). "Additionally, scientists suggest that G‐17 is more suitable as a noninvasive biomarker of atrophic gastritis than total gastrin and it's the major form of the antral hormone gastrin in plasma or antral mucosal tissue, can regulate the secretion of gastric acid and the growth of gastric mucosal." (PMID 36705412, 2023). "Moreover, a study suggested that testing for pepsinogen I, pepsinogen II, pepsinogen I to pepsinogen II ratio, and gastrin-17 may diagnose any type of atrophic gastritis." (PMID 35458234, 2022). "Evaluation of serologic markers for atrophic gastritis, such as gastrin-17, pepsinogen-1, pepsinogen-2, the pepsinogen-1/pepsinogen-2 ratio was developed by Biohit; however, this evaluation did not allow us to determin the degree of stomach mucous membrane atrophy in cases of atrophic gastritis." (PMID 32102507, 2020). "However, it is necessary to underline that this test can be positive also in patients with hypergastrinemia due to atrophic gastritis, in fact, it has been shown that antral G-cells have secretin receptors and release gastrin when stimulated with pharmacological doses of secretin." (PMID 24213321, 2012). "Eight out of nine cases were classified as type 1 with elevated gastrin levels and EGD findings of atrophic gastritis—“gastric mucosa with moderate chronic active gastritis and intestinal metaplasia”." (PMID 40217599, 2025). "Pathological characteristics and levels of gastrin 17 (G17), pepsinogen (PG) I and II and anti-Helicobacter pylori IgG were assessed in GPL cases, and the severity of intestinal metaplasia and gastric atrophy was scored by expert pathologists." (PMID 37834796, 2023). "The mechanism of HIV-related induced hypochlorhydria in this setting remains unclear, but appears to be associated with a chronic pangastritis as evidenced by the histology, and resulting high fasting serum gastrin concentrations, and does not appear to be caused by gastric atrophy." (PMID 26244370, 2015).
atrophic gastritis (continued). "Despite serum gastrin concentrations comparable to H. pylori-induced atrophic gastritis patients, PPI therapy did not significantly affect the gastric flora." (PMID 40843060, 2025). "The gastrin level over 4 years in patients with severe gastric atrophy and those with no atrophy was in the range of 900–1500 and 500–1000 pg/mL, respectively." (PMID 38919514, 2025). "Without stimulation tests, basal gastrin-17 alone showed 62% sensitivity and 96.1% specificity for diagnosing atrophic gastritis." (PMID 38999928, 2024). "It is reported that gastrin (GAS), pepsinogen I (PG-I), or pepsinogen II (PG-II) might be helpful for non-invasive diagnosis of atrophic gastritis." (PMID 34568580, 2021). "For gastric NETs, the Rindi classification is based on the presence or absence of atrophic gastritis and gastrin secretion." (PMID 35011798, 2021). "Second, we did not measure the plasma levels of ghrelin and gastrin which have been reported to be related to both gastric atrophy and glucose homeostasis." (PMID 28045079, 2017). "Group 4 patients had atrophic gastritis of the antrum and body, with focal intestinal metaplasia of the glands, caused by Hp, and showed absence of PCA and IFA, normal gastrin, and presence of anti-Hp." (PMID 23251219, 2012). "A fasting serum gastrin level of >200 pg/mL should raise the suspicion of the disease, and a level of >1000 pg/mL without the presence of achlorhydria secondary to atrophic gastritis is virtually indicative of ZES." (PMID 16042772, 2005). "Further, there was no endoscopic finding of corpus predominantly atrophic gastritis indicating AIG, and the patient’s serum gastrin level was normal, which is high in AIG." (PMID 40319445, 2025). "In a multicenter prospective study, the VPZ group showed significantly higher serum gastrin levels than the PPI group, in patients with no or mild gastric atrophy." (PMID 38919514, 2025). "However, in these studies, patients with confounding factors, such as active H. pylori infection and/or the presence of atrophic gastritis were not excluded, thus making it difficult to determine whether these confounding factors or PPI usage primarily drive increased gastrin concentrations." (PMID 34867785, 2021).
gastritis (64 papers, 2003 to 2025). Inflammation of the stomach. "Specifically, we first retrieved the MalaCards database to obtain the genes with the highest scores associated with gastritis and fatty liver, namely GAST and PPARA." (PMID 39563444, 2024). "In serum, this study found the levels of gastritis‐associated cytokines, gastrin, PGI, PGII, and gastrin‐17, were significant differences." (PMID 36705412, 2023). "We used the upper limit of this normal range of serum gastrin concentrations and performed a validation study to determine its usefulness as a diagnostic marker for distinguishing between cases of gastritis and true A in the endoscopically-evaluated group." (PMID 37210509, 2023). "Importantly, the serum gastrin concentration evaluated in this study showed high diagnostic performance for identifying patients with gastritis in the endoscopically-evaluated group." (PMID 37210509, 2023). "In addition, ROC curves showed high diagnostic performance of gastrin for gastritis, with an area under the ROC (AUC) curve of 0.80." (PMID 37210509, 2023). "Furthermore, some cytokines that induce G cells to secrete gastrin, such as ammonia and tumor necrosis factor-alpha, are released in H. pylori-associated gastritis, which further upregulates the gastrin levels." (PMID 35126509, 2022). "Finally, antral predominant H. pylori-associated gastritis has also been reported to locally decrease the expression of the gastrin-inhibiting peptide somatostatin." (PMID 34867785, 2021). "Gastritis induced by HP infection could affect the secretion of gastric-related hormones such as leptin, ghrelin, gastrin and somatostatin, which might influence a predisposition to DM." (PMID 30779804, 2019). "Gastritis caused by H. pylori may affect the secretion of gastric-related hormones, such as leptin and growth hormone-releasing hormone, as well as gastrin and somatostatin, which may affect the susceptibility to diabetes." (PMID 31583248, 2019). "Our previous study showed that long-term rebamipide treatment improved histologic gastritis in terms of mononuclear cell infiltration into the antrum and corpus and resulted in decreased serum gastrin levels in patients with H. pylori-associated gastritis for 1 year." (PMID 26060821, 2015). "Histamine, released from enterochromaffin-like (ECL) cells in response to stimulation of the gastric mucosa by gastrin and acetylcholine, causes increased secretion of gastric acid during gastric irritation or inflammation and damages the mucous membrane, thereby aggravating gastritis symptoms." (PMID 39861107, 2025). "It has been reported that the release of gastric-related hormones may be influenced by H. pylori-induced gastritis, and among these hormones, leptin, hunger hormone, gastrin, and growth inhibitor all affect the susceptibility to diabetes and promote obesity and diabetes." (PMID 38652719, 2024). "Then we retrieved the PDB database and obtained the protein 7F8V contained in the gene GAST related to gastritis and the protein 6LXA contained in the gene PPARA related to fatty liver." (PMID 39563444, 2024). "Accordingly, the 24-h gastrin exposure in persons with H. pylori gastritis is higher than fasting gastrin values indicate." (PMID 37941554, 2023). "And this type of gastritis usually resulted in increasing gastric acid secretion, and even duodenal ulcers because the parietal cells were hyper-stimulated by the gastrin and somatostatin-secreting cells due to antral inflammation." (PMID 38129568, 2023). "The gastrin cut-off value of 126 pg/mL has a good positive predictive value (97.0%) for detecting gastritis positing its use as a marker for cases requiring endoscopy." (PMID 37210509, 2023). "A meta-analysis also reported that a combination of serum PG, gastrin, and anti-Hp Abs is useful in the diagnosis of gastritis." (PMID 37210509, 2023). "And we showed the usefulness of a serum gastrin cut-off value focusing on distinguishing gastritis cases from normal stomach cases in this study." (PMID 37210509, 2023).
gastritis (continued). "The gastrin cut-off value of 126 pg/mL has a good positive predictive value (97.0%) for detecting gastritis, suggesting that it can be used as a marker for recommending endoscopy." (PMID 37210509, 2023). "Serum gastritis markers (Gastrin 17, Pepsinogen I and II) can be invoked as auxiliary diagnostic and predictive indicators." (PMID 37788485, 2023). "In this study, we aimed to identify the normal serum gastrin concentrations in normal stomach cases based on pathological diagnosis and investigate the usefulness of serum gastrin concentrations in diagnosing gastritis." (PMID 37210509, 2023). "Clinicians should also note that AIG can be suspected by serology, especially when false negative or positive results are suspected or during serological screening for gastritis involving PG and/or gastrin." (PMID 35273265, 2022). "At present, gastritis is mainly divided into gastroscopy and laboratory examination, which included gastric juice analysis, pepsinogen test, serum gastrin test, and Helicobacter pylori test." (PMID 34222007, 2021). "On the other hand, there is still a significant controversy, if a rise in plasma gastrin is responsible for the development of gastritis and gastric ulcers in sled dogs." (PMID 34765666, 2021). "Normal gastric mucosal development requires gastrin, somatostatin, and H+K+ATPase; however, all three are greatly diminished in mice with gastritis and tumorigenesis." (PMID 32231118, 2020). "At that time gastritis was very prevalent, and many persons with gastritis were included in establishing the normal range of gastrin." (PMID 32796591, 2020). "In such patients with pyloric-predominant gastritis and potent acid secretion, eradication reduces gastrin stimulation by IL-8 and normalizes acid secretion, which is expected to prevent reflux esophagitis." (PMID 32961949, 2020). "Release of gastrointestinal and stress-related hormones, like gastrin and cortisol, has been proposed as potential contributors to exercise-induced gastritis and gastric ulcers in sled dogs." (PMID 27112583, 2016). "IL-1β was also up-regulated in the stomach of our gerbils with gastritis and in the present study, gastrin mRNA was up-regulated in the fundus of gerbils inoculated with strains ASB2 and ASB6." (PMID 23895283, 2013). "Levels of pepsinogens, gastrin, and percentage of subjects seropositive for H. pylori, and CagA according to the topography of moderate/marked gastritis and atrophy." (PMID 22066020, 2011). "This probably depends on the higher levels of gastrin that occur in AAG as they cause a form of corpus-restricted gastritis and the sparing of the antrum does not affect the production of gastrin by G cells." (PMID 38999928, 2024). "Serum gastrin, which is produced in antral G cells and therefore tends to rise with gastritis affecting the corpus and fall with antral-predominant atrophic gastritis, and H. pylori serology have been combined with the pepsinogen I/II ratio to improve performance." (PMID 37568729, 2023). "Several studies have reported on serum gastrin concentrations in gastritis cases and on the fact that gastrin concentrations are elevated in gastritis and can be a marker of gastritis; however, the gastrin concentrations in these studies were measured without prior pathological evaluation." (PMID 37210509, 2023). "However, if the gastrin concentration is above the cut-off value, the possibility of gastritis is high." (PMID 37210509, 2023). "The combination of serum PG, gastrin, and anti-Hp Abs was useful for diagnosis of gastritis." (PMID 37210509, 2023). "However, the identification of patients with gastritis having normal serum gastrin concentrations due to insufficient sensitivity remains a challenge for the future." (PMID 37210509, 2023). "Furthermore, we evaluated the validity of this gastrin cut-off value in diagnosing gastritis in a separate group that was evaluated endoscopically." (PMID 37210509, 2023).